IL33 (interleukin 33)
Diseases named in the same sentence as IL33 in open-access papers (continued):
Sharing a sentence is not in itself a finding about the gene and the disease.
asthma (continued). "Among our genes that were driven by rare variants, i.e., ALOX15, CSF2RB, IL17RA, IL33, JAK2, S1PR4, and SH2B3, previous studies supported a rare variant association between IL33, which is a known asthma locus, and eosinophil count." (PMID 35935937, 2022). "Clinical trials have demonstrated the efficacy of itepekimab an anti-IL-33 mAb, and astegolimab, an IL-33 receptor inhibitor, in adult asthma outcomes." (PMID 35743783, 2022). "Our study showed that IL-33 levels were elevated in patients with ABPA and CPA and that IL-33 levels were notably higher in patients with CPA than in those with asthma and significantly higher in those with CPA with fungus balls on chest CT." (PMID 35628692, 2022). "A genome-wide association study by Moffatt's team involving 10,365 patients with asthma and 16,110 normal controls found that there was a significant genomic correlation between the single-nucleotide polymorphisms of IL-33 and IL1-RL1 and asthma." (PMID 35578178, 2022). "Etokimab is another anti-IL-33 monoclonal antibody which has been recently studied as a possible asthma treatment." (PMID 36561741, 2022). "IL-33 is highly expressed in bronchial epithelium of patients with asthma with increased expression after exposure to environmental triggers such as allergen." (PMID 35406669, 2022). "Therapies targeting mast cell mediators and/or their receptors, including monoclonal antibodies targeting IgE, IL-4/IL-13, IL-5/IL-5Rα, IL-4Rα, TSLP, and IL-33, have been found safe and effective in the treatment of different phenotypes of asthma." (PMID 36430941, 2022). "A meta‐analysis in 2,007 children in Prevention and Incidence of Asthma and Mite Allergy (PIAMA) and 7,247 in ALSPAC found that SNPs encoding IL33 and IL1RL1 were associated with asthma, intermediate and late‐onset wheeze phenotypes." (PMID 35338742, 2022). "While prospects are promising for prevention of TSLP-mediated inflammation through tezepelumab, therapies against the other two alarmins, IL-25 and IL-33 are currently lagging as effective treatments in asthma." (PMID 36311787, 2022). "Currently, clinical trials are assessing the efficacy of anti-IL-33 monoclonal antibody treatments (Itepekimab, Etokimab and Tozorakimab) in chronic obstructive pulmonary disease, asthma, atopic dermatitis and peanut allergy." (PMID 38566909, 2022). "Neonatal RV infection resulted in induction of IL-33, IL-25, and TSLP–all of which are epithelial derived cytokines implicated in asthma pathogenesis–and in this model contributed to type 2 innate lymphoid cells (ILC2) expansion." (PMID 35493465, 2022). "Due to its enhancing effect on type 2 cytokine secretion, approaches to neutralise IL-33 are currently being developed for asthma therapy and have shown a reduction in exacerbation rates." (PMID 36366528, 2022). "IL-33 expression is increased in airway epithelial cells of patients with asthma or chronic obstructive pulmonary disease and in mouse type 2 alveolar epithelial cells by pathogens and allergens." (PMID 36291105, 2022). "Compared with the healthy control group, the expression level of IL-33 in airway epithelial cells of asthma patients was higher." (PMID 35578178, 2022). "Previous data reported various cytokines, such as IL-4, IL-5, IL-13, and IL-33, increased in patients with asthma and AR in serum or lower respiratory tract specimens." (PMID 35348596, 2022). "The IL-33/ST2 axis has been most studied in the context of asthma, where IL-33 both enhances allergic responses and plays a pivotal role in antigen-independent responses." (PMID 35493481, 2022). "The mechanisms through which IL-33 and IL-25 differentially counter anti-viral responses suggest that alarmin cytokines can promote asthma severity culminating from various viral infections, which can be harnessed as treatment strategies." (PMID 36311787, 2022).
asthma (continued). "Subsequently, the expressions of potential biomarkers were examined through qRT-PCR analysis in the T2 asthma coreinteracting cellular factor (IL-13/IL-33) induced experimental model." (PMID 35480331, 2022). "In asthma, allergic airway inflammation is initiated by IL-33 signaling through ST2, leading to increased IL-4, IL-5, and IL-13 production and eosinophil infiltration." (PMID 35025767, 2022). "The epithelium-derived cytokines IL-33, TSLP, and IL-25 have been implicated in pathogenesis of asthma because they promote type 2 cytokine synthesis." (PMID 35524325, 2022). "Genome-wide association studies have indicated that IL-33 and IL1RL1 (encoding ST2), which have obvious links to ILC2 biology, are associated with asthma susceptibility." (PMID 35911708, 2022). "Among these, LPS, IL-17, IL-33, CXCL8, C3a/C5a and IL-1β, which have been implicated in various aspects of asthma, are inducers of NET formation in neutrophils." (PMID 34342773, 2022). "IL-1β has been shown to induce neutrophilic asthma and IL-33 expression in a mouse model of asthma with viral infection exacerbation, and was a key cytokine in induction of airway smooth muscle hypersensitivity." (PMID 35626330, 2022). "One study has indicated that multiple feedback circuits involving IL-33 and type 2 innate lymphoid cells (ILC2s) are necessary for persistence of asthma." (PMID 35546400, 2022). "Astegolimab is an anti-ST2 antibody that blocks IL33 signaling and has shown promise in reducing asthma exacerbations." (PMID 36685501, 2022). "IL-13 or IL-33 stimulation of 16 human bronchial epithelial (16HBE) cells was conducted to simulate the cell environment of T2 asthma." (PMID 35480331, 2022). "Among these, the antibody directed against TSLP and an IL-33 inhibitor have been shown to be effective in the treatment of asthma." (PMID 36359220, 2022). "In the last decade, studies have identified IL-33 as a potential culprit in numerous inflammatory diseases such as asthma, inflammatory bowel disease (IBD), rheumatoid arthritis, systemic sclerosis and systemic lupus erythematosus (SLE)." (PMID 35328556, 2022). "IL-1β plays a key role in neutrophilic inflammation during viral-induced asthma exacerbations with increased expression of IL-33." (PMID 36501052, 2022). "The function of sST2 as a down regulator of IL-33 signaling was first discovered in a murine asthma model, BALB/C mice were challenged with OVA to confirm the increasing expression of both ST2 and sST2." (PMID 36311787, 2022). "Allergens, toxic substances, and viral infections cause the release of IL-25, IL-33, TSLP cytokines, the so-called alarmins, from the airway epithelium and induce type-2 inflammation via ILC2 and Th2 cells in asthma." (PMID 36326393, 2022). "Here we therefore aim to appraise the available evidence for the effect of anti-IgE, anti-IL5 (Rα), anti-IL4Rα, anti-TSLP and anti-IL33 biologics on small airways disease in patients with severe asthma." (PMID 36239786, 2022). "Another biologic that directly targets IL-33, itepekimab, was recently found to improve lung function and lower the incidence of uncontrolled asthma events in a monotherapy cohort of a phase II trial in asthma." (PMID 36311787, 2022). "In the lower airways, the release of IL-33 has been proposed to be responsible for the development and exacerbation of airway hypersensitivity and asthma." (PMID 35406669, 2022). "Airway administration of OM-85 blocked experimental asthma in mouse models by targeting dendritic cells and the epithelium/ IL-33/ILC2 axis." (PMID 35743678, 2022). "The formation of pathophysiological features of asthma can occur through the release of pro-inflammatory cytokines such as interleukin (IL) 1β and IL-6, while epithelium-derived IL-33 promotes Th2 differentiation." (PMID 36141448, 2022).
asthma (continued). "In consideration of the role that IL-33 plays in the severe asthma exacerbations evoked by rhinovirus, this makes it one of the potential targets of anti-IL-33 monoclonal antibody biotherapy." (PMID 35327516, 2022). "Epithelial-derived cytokines [i.e., TSLP, IL-33, IL-25] act as upstream cytokines in asthma pathobiology." (PMID 36359917, 2022). "IL-33 is an epithelial-derived alarmin cytokine that plays a significant role in the pathobiology of allergic disease and asthma." (PMID 36292755, 2022). "Accumulating evidences showed that asthma and IL-33 signaling were related to intestinal inflammation." (PMID 36494354, 2022). "For the emergence of allergic inflammation, such as in asthma, activating the IL-33/ST2-involving Th2/IL-31 immune response is particularly important." (PMID 36341243, 2022). "Many antibodies against alarmins, such as anti-IL-33 antibodies, have been developed and are currently undergoing clinical trials for asthma, chronic rhinosinusitis, and atopic dermatitis." (PMID 35326502, 2022). "Collectively, it is evident that from their prime position in the inflammatory cascade, TSLP, IL-25 and IL-33 orchestrate the elicitation and activity of multiple effector cells and pathways that constitute the asthma phenotype." (PMID 36311787, 2022). "Anti-IL-33 mabs in clinical trials for AD and/or asthma are etokimab (ANB020), itepekimab (REGN 3500), astegolimab (MSTT1041A/ AMG282), and tozorakimab." (PMID 35743678, 2022). "Itepekimab, a monoclonal antibody against IL-33, showed efficacy and safety both as a monotherapy and in combination therapy in patients with moderate to severe asthma." (PMID 35328556, 2022). "As such, IL-33 plays a critical immune-modulatory role in allergic and chronic inflammatory and degenerative diseases, from asthma and cardiovascular disease to Alzheimer’s disease." (PMID 34531552, 2022). "IL-33 appears to play a major role in the initiation and development of type 2 immune responses involved in the development of asthma." (PMID 35807067, 2022). "The genetic sequences encoding IL33 and IL-1 receptor-like 1 (ILRL1), which encodes ST2, are amongst the few genes associated with asthma." (PMID 36311787, 2022). "IL-33, CXCL8, IL-17, C3a/C5a, IL-1β and LPS, associated with asthma pathophysiology, are important inducers of NET formation." (PMID 36359917, 2022). "Itepekimab, found in the literature under the aliases REGN-3500 or SAR440340, is an anti-IL33 antibody that has recently been studied or treating asthma." (PMID 36561741, 2022). "Randomized controlled clinical trials have demonstrated benefit when blockade of TSLP and IL-33 were added to standard of care medications, suggesting these are important new targets for treatment of asthma." (PMID 35406669, 2022). "Asthma is a type 2-mediated inflammatory disease, and the alarmins interleukin-25 (IL-25) and interleukin-33 (IL-33) play essential roles in shaping the Th2 response signature found in asthma." (PMID 35444658, 2022). "RV infection induced IL-33 and Th2 cytokine responses in the airways of asthma patients, with IL-33 levels correlating with IL-5 and IL-13 levels." (PMID 36077310, 2022). "With both astegolimab and itepekimab continuing in clinical trials, there is still opportunity for the development of effective IL-33 biologics for treating asthma." (PMID 36311787, 2022). "It is possible that chymase-induced IL33 modulation accounts for the beneficial effects in severe asthma." (PMID 36494835, 2022). "IL-33 biologics have shown limited progress in exploring their use for asthma treatment, despite having been tested in more clinical trials than those of IL-25." (PMID 36311787, 2022). "RV infection has been suggested to be associated with the development of asthma, and RV16 infection upregulates TSLP and IL-33 expression in human lung epithelial cells." (PMID 35292112, 2022).
asthma (continued). "The impact of IL-33 on MCs may have important consequences in viral-induced exacerbations of asthma: IL-33 release by a virally infected epithelium may predispose MCs for increased infectivity by HRV allowing MCs to contribute in a detrimental way to rhinovirus induced exacerbations of asthma." (PMID 36366528, 2022). "Recently, several studies showed that epithelium-derived cytokines, namely IL-25, IL-33, and TSLP, act as key regulatory factors in immune-pathogenic mechanisms of allergic rhinitis, asthma, and CRSwNP mainly involved in type 2 inflammatory responses." (PMID 35162939, 2022). "There are ongoing human clinical trials assessing the efficacy of anti-IL-33 mAbs to treat severe asthma and atopic dermatitis." (PMID 33669458, 2021). "Initial studies that looked at anti-IL-33 agents were done in other sites of allergy beside asthma, specifically in atopic dermatitis and peanut allergy." (PMID 35126131, 2021). "So, activation of Nrf2 expression leads to control of Th2 cytokines and upper hand of these cytokines (IL-33), and can be attenuate allergic and inflammation related agents and allergic rhinitis and asthma." (PMID 33743807, 2021). "The results showed that the levels of IL-6, IL-8, and IL-33 were markedly increased in serum of patients with asthma in comparison with that of healthy subjects (p < 0.01)." (PMID 33506046, 2021). "For example, in a mouse model of ovalbumin-induced asthma administration of anti-IL-33 antibodies was shown to decrease eosinophil infiltration, IgE production and Th2 cytokine release, as well as airway hyperreactivity (AHR)." (PMID 34084159, 2021). "Predictive interaction analysis revealed strong physical interactions between IL1RL1 and TMED1 which is unsurprising as both are related to IL33 signaling which has been extensively researched in the context of asthma." (PMID 35386986, 2021). "There are multiple RCTs underway assessing the efficacy of anti-IL-33 biologics to treat asthma, but most results are pending." (PMID 35126131, 2021). "The current studies identify unique features of viral infection (RSV), asthma (OVA) and viral induced asthma exacerbation (OVA-RSV) mediated by IL-33." (PMID 34266437, 2021). "We observed a marked increase in the levels of epithelial cell–derived cytokines Tgf-β1, Tslp, IL-25, and IL-33 in BALF of allergen-induced mouse models of asthma." (PMID 34101619, 2021). "In a mouse model of IAV-induced asthma exacerbation using the Sendai virus, it was also found that viral infection induced an early spike in il-33 gene expression followed by a second more intense phase that persisted for several weeks after viral clearance." (PMID 34960788, 2021). "In other chronic inflammatory conditions, such as asthma, type 2 diabetes, and atopic dermatitis, elevated levels of IL-33 activate ILC2s to perpetuate type 2 inflammation and aggravate the symptoms of the disease." (PMID 34699382, 2021). "IL-33 expression is increased in the lungs and airways of patients with asthma and correlates with disease severity." (PMID 34960788, 2021). "In contrast, asthma pro-inflammatory cytokines such as IL-4, IL-5, IL-13, and IL-33 contribute to maintain the lean state." (PMID 33418879, 2021). "Recent studies have shown that during viral-induced asthma exacerbations, high levels of IL-33 were produced by airway epithelial cells, consequently suppressing type-I IFN production and leaving the epithelium more vulnerable to repeated infections." (PMID 34868033, 2021). "In the study of children with asthma, it was found that the proportion of Th2 cells and the level of IL-33 in serum increased significantly, which were positively correlated with the level of autoantibody IgE in vivo." (PMID 34395633, 2021). "Several anti-IL-33 monoclonal antibodies are under clinical evaluation as potential biological therapies for asthma." (PMID 34572294, 2021).
asthma (continued). "Of interest, IL-1β signaling has been shown to be critical in inducing neutrophil chemotactic factors, IL-33, and Muc5ac expression at viral-induced asthma exacerbation." (PMID 34868022, 2021). "The IL-33/ST2 receptor complex signal pathway via group 2 innate lymphoid cells (ILC2) has been suggested to play a major role in the pathogenesis of asthma in humans." (PMID 33722239, 2021). "Another large-scale GWAS for asthma has identified six asthma-susceptible loci, including IL1RL1/IL18R1, SMAD3, ORMDL3/GSDM, IL-33, IL2RB, and HLA-DQ." (PMID 34946955, 2021). "In chronic rhinosinusitis with nasal polyps (CRSwNP), a disease related to asthma, various expression patterns of IL-25, IL-33, and TSLP in different populations and regions have been described." (PMID 33945508, 2021). "Alarmins are innate cytokines, including thymic stromal lymphopoietin (TSLP), interleukin-33 (IL-33), and interleukin-25 (IL-25), which are mainly produced by airway epithelium and exert a prominent role in asthma pathobiology." (PMID 34572294, 2021). "Both reduced and oxidized forms of IL-33 can be detected in sputum from patients with moderate to severe asthma." (PMID 35011670, 2021). "Chymase has been assigned a plethora of asthma-related activities, including increasing mucus production, modification of extracellular matrix and modulation of cytokines like IL-33, IL-4, and IL-1β." (PMID 34868033, 2021). "Future studies are required to understand the regulation of this complex role for IL-33 and the impact of IL-33-induced innate memory in human asthma." (PMID 34048460, 2021). "The translational significance of the interactions between IL-33 and bacterial superantigens deserves further investigations in experimental models of asthma." (PMID 33445787, 2021). "IL-33 further contributes to the pathogenesis of airway remodeling in asthma by activating the epithelial–mesenchymal trophic unit, as well as by stimulating fibroblasts to produce extracellular matrix proteins, such as collagen type 1 and fibronectin." (PMID 34572294, 2021). "This study highlights a significant role of IL-33 in viral-induced asthma exacerbation in the well-known OVA animal model where RSV-A2 was used to amplify mucus and type 2 inflammatory markers." (PMID 34266437, 2021). "Studies in individuals with asthma and in mouse asthma models have identified elevated levels of IL-33 protein in both sera and tissues." (PMID 34675193, 2021). "Taken together, our findings indicate a broad reduction in allergic-proinflammatory events mediated by IL-33 neutralization in RSV-induced asthma exacerbation." (PMID 34266437, 2021). "Recent studies have demonstrated that IL-33 levels in sputum, serum, and tissue expression correlated with asthma severity." (PMID 33418879, 2021). "IL-25 and TSLP, although not members of the alarmin family, are cytokines that act together to and share similar features with IL-33 in asthma inflammatory pathways." (PMID 34608100, 2021). "Our findings not only demonstrate the potential role of IL-33 antibody in attenuating RSV-induced lung damage but also provide a new insight into better prevention of RSV-induced asthma by mediating NF-κB/IL-33/ST2 axis." (PMID 34395633, 2021). "Numerous studies have demonstrated that both human and mouse ILC2s are strongly associated with respiratory and allergic diseases, including asthma and that activation of ILC2s requires IL-33 signals." (PMID 34194431, 2021). "This study provides evidence for the association of asthma susceptibility, eosinophilic airway inflammation, and efficacy of ICS with distinct IL33/IL1RL1 ligand-receptor complex polymorphisms." (PMID 34977013, 2021). "Alarmins such as thymic stromal lymphopoietin (TSLP), IL-25 and IL-33 can drive allergic inflammation in response to airway damage and their expression correlates with asthma severity." (PMID 34777398, 2021).